CD14 (CD14 molecule)
Diseases named in the same sentence as CD14 in open-access papers (continued):
Sharing a sentence is not in itself a finding about the gene and the disease.
infection (continued). "Surprisingly, and in agreement with our data for HF infected cells, FIX-ΔLUNA infection did not result in detectable expression of UL138 in CD14+ cells using RT-PCR." (PMID 23300789, 2012). "By gating on these CD14+CD16- and CD14+CD16+ monocytes, we could see that the infection rates were similar." (PMID 22574162, 2012). "Although we focused here on the role of IFN-γ in stimulating CD14+ monocytes/macrophages to secrete CXCL9 and CXCL10, other factors and cell types may be involved in the actual infection." (PMID 20828409, 2010). "The dominant part of the CD3 CD19 double negative population constituted of CD16+ CD14- cells and these were the cells which decreased after the infection with virulent S. Enteritidis." (PMID 20226037, 2010). "There was no change in the absolute number of CD14+CD16+ monocytes in the slow progressors throughout infection (data not shown)." (PMID 20419144, 2010). "Among mice that did not develop ECM, between days 6 to 8 post-infection, mean parasite burden was approximately 2-fold lower in CD14-KO mice compared to WT mice (4.2% vs. 8.3% on day 6)." (PMID 19710907, 2009). "A similar trend toward fewer culture-positive mice in CD14 was observed at 28 through 42 days post-infection but this did not prove significant." (PMID 16995947, 2006). "Among the non-T lymphocytes, there was a strong bias towards the infection of CD14 positive cells (monocytes), of which up to 77% showed green fluorescence, followed by B lymphocytes (CD19+, up to 20%) and NK cells (CD56+, up to 9%)." (PMID 15555076, 2004). "No adverse events (including signs of infection) were observed following treatment with anti-CD14 antibody either in vivo or at postmortem in any of the present studies (postmortem examinations performed for all animals, including all 102 mice following treatment with anti-CD14)." (PMID 41134248, 2025). "Importantly, both CD14 and TLR2 have been suggested for targeted therapy in an infection context." (PMID 41307706, 2025). "Likewise, menopausal status did not alter mean CD14+ cell infection frequency in the EM, CX nor ECX." (PMID 39872519, 2024). "Moreover, by interpreting the decision patterns of our classification system, we identified that different immune cells upregulating or downregulating the expression of the genes CD3, CD14, CD16, FOSB, S100A12, and TCRɣδ can accurately differentiate between different degrees of infection." (PMID 38892107, 2024). "Within the pre-infection immune cell population, 17.3 ± 1.3% were CD4+ T cells, 21.5 ± 3.1% were CD8+ T cells, 1.8 ± 0.3% were NCR1+ NK cells, 12.8 ± 2.3% were IgM+ B cells, 5.4 ± 0.7% were IgG1+ B cells, 5.9 ± 0.6% were CD14+ monocytes, and 4.9 ± 0.9% of immune cells expressed cell surface CD25." (PMID 39459849, 2024). "As the results described in this paper confirm, CD14 gene expression is increased by LPS in alveolar macrophages after several hours of infection, TLR4 gene expression is decreased by LPS infection of mouse macrophages, and MD2 gene expression is higher after LPS infection of alveolar macrophages." (PMID 38785798, 2024). "Thus, constitutive activation of Rho-GTPases in CDC42hi CD14+ cells and STM of RA patients could be a mechanism triggering immunoproteasome domination similar to that described during an infection." (PMID 37662900, 2023). "In addition, CD14+ monocytes increased by a factor of 0.97–16.3% throughout critical infection, signifying that the overall immunological milieu encouraged the expansion and recruitment of monocytes in response to MPOX infection." (PMID 37533932, 2023). "Importantly, these CD14+ PMNs expressed APP antigens and exhibited the characteristics of apoptotic cells, as they highly expressed CD24 and CD36, markers of apoptotic PMNs, indicating that these cells play a key role in the recovery stages of infection." (PMID 37705063, 2023).
infection (continued). "Within the CD14+CD16- classical monocyte compartment, expression of FcγRI increased significantly during the acute phase of DENV infection while the expression of FcγRIIa remained unchanged and the expression of FcαR was reduced relative to pre-infection levels." (PMID 37639455, 2023). "The observation that platelets do not express CD14 but can absorb a large amount of sCD14 from the plasma is also of physiological relevance, as platelets are not primary defenders in infection, but need to act in concert with immune cells that release sCD14 to trigger LPS–TLR4 signaling." (PMID 36142813, 2022). "To study the function of human GBPs in the context of controling Tg infection, we utilized three distinct human macrophage culture systems: PMA-differentiated THP-1 macrophages, KOLF iPSC and in vitro differentiated macrophages of purified primary CD14+ monocytes from blood of healthy donors." (PMID 34931666, 2022). "Furthermore, we found the TLR4/CD14/MD2 complex to be decisive for the uptake of Ct-derived lipopolysaccharides but not for infection and replication of Ct." (PMID 36557742, 2022). "CD14 is an early detector of tissue damage and infection, and a lack of CD14 could potentially disrupt the gene-expression of cytokines." (PMID 35954192, 2022). "The percentages of CD21+ (B cells), WC1+ (γδ-T cells), CD4+ (helper T cells), CD8+ (cytotoxic T cells), CD14+ (monocytes/macrophages) and CD335+ (NK) cells were studied in the population of PBMC from G-NcSpain7, G-NcSpain1H and G-Control by flow cytometry at different times post-infection." (PMID 34239816, 2021). "The partial dependence diagrams show a positive correlation of infection with the following variables: MFI of CD64 on CD14lowβ7-CD16+ monocytes and neutrophils, MFI of CD14 on CD14lowβ7-CD16+ monocytes, MFI of CD16 on monocytes, percentage and MFI of integrin β7 on CD14+CD91low monocytes." (PMID 34645893, 2021). "Overall, exposure to PRRSV1 did not induce maturation of cDC1, cDC2, or CD14+ DCs, but modified TLR3 and TLR7-associated responses (except for cDC1), which may affect the development of adaptive immunity during PRRSV1 infection." (PMID 34177915, 2021). "We found that the percentages of α2,3 SA+ CD14+ B cells in the H5N1 infection were 0.430±0.36%, 4.04±0.99% and 4.92±1.68% at 0, 12, 24 hours, respectively, and were significantly higher than in the mock infection (0.13±0.13%, 0.52±0.438 and 0.76±.26% at 0, 12, 24 hours, respectively)." (PMID 32946496, 2020). "Down regulation of ADAM17 inhibition may also impair the immune responses and increase the susceptibility to infections, due to imbalance in the release of CD14, CD16 via monocytes, natural killer cells, and T cells and also due to impaired neutrophil infiltration at the sites of infection." (PMID 32848763, 2020). "Among non-PMN myeloid cells, there were few CD38+CD14+ cells two weeks after infection." (PMID 32544188, 2020). "Thus, the differential expression of CD14 and CD16 in infected cells results from increased infection of the DP cells, rather than increased expression of CD14 on classical and CD16 on non-classical monocytes." (PMID 33159858, 2020). "Moreover, overexpression of CD14, observed in this study, following exposure to the lowest concentration of bisphenol A (16 nM) may result in an elevated risk of systemic inflammation during infection with Gram-negative bacteria in individuals exposed to this xenoestrogen." (PMID 32080224, 2020). "Furthermore, infection of whole blood of healthy pregnant women with MR766 and H/PH/2013 revealed that CD14+ monocytes are the primary PBMC target also during pregnancy and that MR766 isolate induced a more robust infection in these cells than the H/PH/2013 isolate." (PMID 31752731, 2019).
infection (continued). "The reduced ascites macrophage CD14 and HLA-DR expression and low macrophage phagocytic capacity reported in patients with SBP compared to sterile ascites probably reflects dilution by the CD14Low monocyte-derived macrophage population in the setting of infection." (PMID 30873165, 2019). "Additionally, we wanted to address whether the monocyte subset perturbations observed during infection is real or an artifact of differential CD16 and/or CD14 regulation." (PMID 31402918, 2019). "However, unlike in CD34+ cells, MCL-1 levels remain elevated in CD14+ monocytes until at least 48 h post infection (hpi), a long time after the initial binding events responsible for triggering its upregulation." (PMID 29547547, 2018). "To assess whether infection changed the expression of junctional proteins essential to CD14+ CD16+ monocyte transmigration, we examined surface JAM-A and ALCAM on HIV+ and HIVexp CD14+ CD16+ monocytes." (PMID 29066542, 2017). "To characterize the mechanisms of viral infection of the CNS and to determine potential therapeutic targets that may limit the infection and continued replenishment of CNS viral reservoirs by HIV+ CD14+ CD16+ monocytes, we examined their transmigration across an in vitro model of the human BBB." (PMID 29066542, 2017). "However, some studies have demonstrated both positive and negative effects of CD14 on infections, depending on the microorganism and the site of the infection." (PMID 27252945, 2016). "We aimed to evaluate the roles of the plasma immune activation biomarkers neopterin and soluble CD14 (sCD14) in the indirect assessment of the immune activation status of patients with the indeterminate HIV-1 (IHIV-1) pattern and a true HIV-1-positive infection (PCG)." (PMID 27031691, 2016). "The reported dichotomy of BDCA3+ dermal DC emigration but not of dermal CD14+ cells into lymphatic vessels could be examined in a natural infection setting in our inner foreskin explant system." (PMID 25875649, 2015). "However, infection with AT-2-inactivated JR-FL did not significantly affect the maker expressions in CD14-derived osteoclasts." (PMID 25809599, 2015). "At least for dermal DCs, expression of these two receptors could therefore explain the more efficient infection of CD14+ DCs compared to CD1c+ DCs and the absence of infection in CD141+ DCs." (PMID 25474532, 2014). "Alternatively, infection of CD14+ DCs could affect their capacity to induce regulatory CD4 T cells in the skin, a function that has been associated with CD14+ DCs and not with CD1c+ DCs." (PMID 25474532, 2014). "In contrast to CD14+ DCs, infection of CD1c+ DCs and LCs did not impair their capacity to induce allogeneic CD4+ T cell proliferation, showing that DENV-mediated inhibition of T cell proliferation was DC subset specific and not a direct generic effect of the virus either on DCs or T cells." (PMID 25474532, 2014). "However, even in the absence of infection or lactation, CD14 and other genes involved in innate immunity are highly induced during regression of the mammary gland after weaning." (PMID 24982636, 2014). "In conclusion, the contribution of CD14 to infection control may be either positive or negative depending both on the microorganism and the site of infection." (PMID 23898465, 2013). "In this regard, Ly6Clow non-classical monocytes in mice, which are homologous to CD14 dimCD16+ monocytes in humans, have been reported to patrol in search of signs of infection or tissue damage, and rapidly exit vessels to reach the inflammation site within several hours after infection." (PMID 23936327, 2013). "Typically CD14+ cells are not able to support lytic infection, and thus may not be capable of proper expression of this late gene." (PMID 23300789, 2012).
infection (continued). "Importantly, other than mesenteric Cd14+ macrophages and neutrophils, none of the genes examined was more highly induced in the other cell types of ΔNS1-infected bats, indicating that WT and ΔNS1 infection elicited similar innate immune responses." (PMID 38802391, 2024). "However, our study showed a significantly decreased TNF-α production in CD4+, CD8+ T cells and CD14+ monocytes in TB, and HIV co-infected with TB had obviously decreased TNF-α production in CD4+, CD8+ T cells and CD14+ monocytes under a natural infection status without external antigen stimulation." (PMID 37483385, 2023). "Moreover, cervical myeloid dendritic cells (CD14+ CD11c+) have been shown to efficiently take up R5-HIV strain, more so than lymphocytes (CD4+/low) and macrophages (CD14+ CD11c−) but do not show signs of productive infection at a later time point, unlike the lymphocyte population." (PMID 31156637, 2019). "Thus, inhibiting signals through CD14 may limit the release of a broad range of inflammatory mediators, and prevent rapid bacterial dissemination following infection by Gram-negative bacteria." (PMID 25889660, 2015). "However, not all signaling pathways are inactivated by Yersinia during infection, and inhibition of c-KIT may lead to redirection to alternative signaling pathways, such as the LPS-activated CD14 and TLR4 signaling to p38 and JNK, to recover NF-KB-driven gene expression." (PMID 24206648, 2013). "Unlike the tissues, peripheral blood CD14+ monocytes/macrophages and cDC in INF subjects did not express higher HLA-DR post-infection, highlighting localized differences in the impact of infection in upper respiratory tract tissues compared to blood." (PMID 40964019, 2025). "Infection of these cells by EBOV can be affected by the polarization state, which has historically been classified using CD14 and CD16: classical (CD14+CD16-, M1) and non-classical (CD14-CD16+, M2) macrophages." (PMID 39635525, 2024). "Another study also found that patients with PASC had significantly elevated levels of both intermediate (CD14+, CD16+) and non-classical (CD14−, CD16+) monocytes up to 15 months post-infection." (PMID 37233729, 2023). "CD93 and FCGR2A (encoding CD32/FcγRIIa) which mediate the enhancement of phagocytosis in monocytes and macrophages were upregulated during infection on CD16+ monocytes and cDCs, but not CD14+ monocytes." (PMID 37968278, 2023). "In detail, Kwissa and colleagues have shown that CD14+CD16+ monocytes were increased in both humans and non-human primates shortly after infection with the dengue virus and that these cells were able to stimulate the differentiation of plasmablasts." (PMID 35042529, 2022). "In humans, in Phase 1 trials, the treatment with a chimeric CD14 antibody (IC14) showed to protect to LPS induced systemic inflammatory response, and it did not increase the incidence of secondary infection." (PMID 35429403, 2022). "A 125 μM concentration of the compound was found nontoxic to the CD14+/CD11b+ cells, and the cells collected from three healthy individuals were subjected to CHIKV infection (multiplicity of infection [MOI] of 5) followed by treatment (100 μM)." (PMID 35766508, 2022). "In contrast to the major changes in CD14+ monocytes, CD16+ monocytes (PBMC myeloid population 5) did not increase in relative abundance after infection." (PMID 35271298, 2022). "While the levels of most of the detected CD markers were not affected by ASFV infection, CD14 and CD74 levels significantly dropped after infection." (PMID 34835004, 2021). "Studies in humans reveal that infection with DENV reduces both the number and frequency of non-classical CD14+CD16++ monocytes, which produce TNF and show a more activated phenotype than cells from healthy controls." (PMID 33829283, 2021).
infection (continued). "This revealed an increased frequency of ‘transitional’ CD14+ CD16+ and ‘non-classical’ CD14− CD16+ monocyte subsets in PBMCs collected at the later post-infection time point in both rhesus and cynomolgus species." (PMID 33627662, 2021). "TNF-α expression increased significantly upon infection with M.tb MOI 1 and MOI 5 or stimulation with PPD, PHA, and LPS in CD3+ T cells and in CD14+ cells compared to uninfected and no-PM control PBMC." (PMID 31731429, 2019). "At 6 months post-infection, SIV-PAH+ animals had higher numbers of peripheral blood CD14dimCD16+ non-classical monocytes (P = 0.06) and CD14+CCR7−CD163−CD206+ BALF macrophages (P = 0.04) compared to SIV-PAH− controls." (PMID 31882598, 2019). "Following infection of primary lymphocytes, SV40 DNA was detected in CD19+ B cells and CD14+ monocytes, but not in CD3+ T cells." (PMID 29432481, 2018). "In the presence of HSV-1, CD14 expression was reduced in both PBMC and lymph node compared to that in mice without infection in all treated groups." (PMID 28096567, 2016). "FIX-WT and FIX-Rev infection of both HF cells and CD14+ cells resulted in expression of the LUNA protein, but not in FIX-ΔLUNA infection." (PMID 23300789, 2012). "We examined the effect of the ChAdOx1 nCoV-19 vaccine on the frequencies of the total monocyte (CD14+) population and nonclassical/intermediate monocytes that coexpress CD16 (CD14+CD16+), which exert effector function in humans during infection and inflammation." (PMID 36282571, 2023). "Furthermore, we demonstrate the complete TLR4/CD14/MD2 complex to be essential for Ct-LPS uptake by cells, but not for uptake and infection of intact Ct." (PMID 36557742, 2022). "Furthermore, we show that infection with WT but not Δβ2.7 virus results in strong upregulation of a cellular antioxidant enzyme, superoxide dismutase 2 (SOD2) in CD14+ monocytes." (PMID 35215840, 2022). "In addition, immunofluorescence analysis of HTNV-infected PBMCs showed infection of MHC class II expressing adherent cells, whereas PBMCs depleted of CD14+ monocytes (PBMCs CD14−) had both fewer adherent cells and no sign of infection." (PMID 32596167, 2020). "Although there were no statistically significant trends between infection groups for CD4+ T lymphocytes, CD8+ T lymphocytes, γδ T lymphocytes, or CD14+ monocytes, the mean change in percentages of CD4+ T lymphocytes appeared to be higher in control animals when compared with infected animals." (PMID 31470560, 2019). "The availability of validated antibodies for rhesus enabled characterization of infected leucocyte subsets, including "inflammatory" monocytes expressing CD14/CD68, dendritic cell phenotypes with CD1a/DCSIGN positivity, but no intracellular infection of T-cells, or endothelial cells was found." (PMID 29522521, 2018). "Green fluorescence could be detected by flow cytometry only in the CD14+ monocytes of PBMC infected with DENV2-eGFP in the presence of 4G2 antibody, but not in B cells, T cells, and NK cells 3 days post infection." (PMID 29547653, 2018). "The percentage of classical (CD14+CD16−), intermediate (CD14+CD16+), and non-classical (CD14−CD16+) monocytes out of the monocyte compartment are shown before infection, during the acute primary infection, and after the peak of infection." (PMID 28938907, 2017). "Here, we demonstrate an increase in intermediate monocytes (CD14++ CD16+) with a concomitant decrease in the classical (CD14++ CD16−) and nonclassical (CD14+ CD16+) subsets at 12 days postinfection (dpi) during lethal infection but not during nonlethal T. parva infection." (PMID 31570561, 2019). "Moreover, increased numbers of CD14dimCD16+ non-classical monocytes (P = 0.04) and CD14+CCR7−CD163−CD206+ macrophages (P = 0.03) correlated with increased pulmonary pressures in SIV/Untreated Group 1 controls at 6 months post-infection." (PMID 31882598, 2019).
infection (continued). "We observed that infection with both strains led to a higher intensity of HLA-DR and TLR-2 expression by infected monocytes (CD14+CFSE+), as compared to media controls; these increases of intensity did not occur in non-infected monocytes (CD14+CFSE-) from the same cultures." (PMID 26147698, 2015). "In vitro infection of mouse bone marrow-derived monocytes (BMDMs) with Ft revealed that by 24 h of co-incubation ∼1.5-log more total bacteria (intra- and extracellular combined) were recovered from TLR2−/−, but not CD14−/−, cells compared to wild-type cells (data not shown)." (PMID 23554897, 2013).